CD4 (CD4 molecule)
Diseases named in the same sentence as CD4 in open-access papers (continued):
Sharing a sentence is not in itself a finding about the gene and the disease.
preeclampsia (continued). "Similar to TIGIT, the expression level of the activating immune checkpoint receptor CD226 was also significantly lower by CD3+ T-, CD4+ T, CD8+ T, and NKT-like cells in women diagnosed with EO preeclampsia compared to the healthy pregnant cohort." (PMID 34829838, 2021). "Analyzing the PD-1 expression by different lymphocyte subsets, CD8+ T cells, CD4+ T cells, and Tregs, NKT-like cells showed a significant upregulation of the PD-1 checkpoint molecule in the case of early-onset preeclampsia compared to healthy pregnant women." (PMID 30700015, 2019). "Therefore, the aim of our study was to assess the population of Treg (CD4+CD25+FoxP3+) and Th17 lymphocytes, as well as the intracellular expression of IL-17A, IL-17F, IL-21, and IL-22 in women with PIH (including preeclampsia)." (PMID 41156157, 2025). "Between the non-pregnant fertile group and preeclampsia, there is a significant difference in lymphocytes and CD4+FOXP3+Tregs." (PMID 39328700, 2024). "CD4+FOXP3 was significantly lower in the preeclampsia group compared to normal pregnancy and non-pregnant fertile women." (PMID 39328700, 2024). "Similarly, when only immunological parameters were considered, CD4+ FOXP3+ % was significant (B = -0.012, Exp(B) = 0.989, Cox & Snell R2 = 0.641, p < 0.001) in detecting preeclampsia." (PMID 37700972, 2023). "Preeclampsia patients were found to have enhanced Lnc-DC expression and STAT3 phosphorylation in the deciduas, along with increased proportion of decidual mature DCs and a bias of CD4+ T cell differentiation into Th1 phenotype." (PMID 29599646, 2018). "This one-dimensional Th1/Th2 paradigm can, however, not fully explain the immunological changes observed during preeclampsia and recent work has expanded the dichotomy to include the Th17 phenotype and a subset of CD4+ T cells known as CD25+ Forkhead box P3 gene (Foxp3+) Tregs." (PMID 30079067, 2018). "Contrary to preeclampsia, in non-pregnant women following recurrent spontaneous miscarriages, higher proportions of EM cells (not specified whether from the CD4+ or CD8+ cell compartment) were observed in peripheral blood compared to fertile non-pregnant controls." (PMID 31001255, 2019).
acute coronary syndrome (39 papers, 2005 to 2025). Signs and symptoms related to acute ischemia of the myocardium secondary to coronary artery disease. "At this moment, we are not aware of studies that strictly compared patients with HIV infection and the associated acute coronary syndrome based on the CD4+ nadir cell count in the literature." (PMID 37627941, 2023). "Our study is longitudinal and retrospective and included a total number of 50 patients with HIV infection associated with acute coronary syndrome, divided into two subgroups based on the nadir of CD4+ cells." (PMID 37627941, 2023). "In T1D and T2D patients, expansion of CD4+ CD28null population is associated with poorer glycemic control and higher excretion of albumin, which predispose a risk of development of acute coronary syndrome." (PMID 34680058, 2021). "We previously demonstrated that circulating CD4+CD28nullT-cell frequency higher than 4% increase the risk of acute coronary syndromes (ACS), particularly in diabetic patients." (PMID 28407684, 2017). "We investigated the effects of ex-vivo and in-vivo atorvastatin treatment in acute coronary syndromes on CD4+T-cells, and the underlying molecular mechanisms." (PMID 28407684, 2017). "After the first episode of acute coronary syndrome, diabetic patients are usually found to be associated with the expansion of CD4+CD28null T-cells, which are manifested as poor glycemic control with worse outcome." (PMID 26751202, 2016). "A direct role of CD4+CD28null T cells in vascular injury has been suggested because these cells are also a risk factor for inflammation and rupturing of atherosclerotic plaques in acute coronary syndromes." (PMID 30995924, 2019). "SELPLG facilitates the homing of cytotoxic CD4 T cells to the coronary arteries, leading to plaque instability in acute coronary syndrome (ACS)." (PMID 40429682, 2025). "Regarding the immune status at the time of the onset of the acute coronary syndrome, most patients (54%) had CD4 + lymphocytes over 500 cells/μL, over a third of them had values between 200 and 500 cells/μL and only 6% had below 200 cells/μL." (PMID 37174918, 2023). "The mean time interval between CD4+ nadir determination and the onset of acute coronary syndrome was similar between the two subgroups (14.07 in subgroup A vs. 13.05 years in subgroup B)." (PMID 37627941, 2023). "Not surprisingly, patients with a nadir of CD4+ < 200 cells/mm3 had significantly lower CD4+ cell count at the diagnosis of acute coronary syndrome." (PMID 37627941, 2023). "While initial studies reported that CD4+CD28null T cells correlate with unstable angina and acute coronary syndromes in humans, this was recently challenged by a multi-center study with a larger number of patients." (PMID 35778407, 2022). "(D) Frequency of CD4+CD28null T-cells in patients with acute coronary syndrome stratified according to cytomegalovirus (CMV) serostatus." (PMID 34289931, 2021). "Acquired immune responses mediated by CD4+ T cells contribute to the initiation and progression of acute coronary syndrome (ACS)." (PMID 33269101, 2020). "Researchers in a recent study reported that OX40 expression was upregulated on CD4+CD28− T cells in patients with acute coronary syndrome and that the secretion of IFN-γ and TNF-α was suppressed by OX40 blockade." (PMID 28320444, 2017). "A novel finding was that circulating CD4+CD28null T cells from acute coronary syndrome patients expressed higher levels of 4-1BB costimulatory receptors compared to classical CD4+CD28+ T lymphocytes." (PMID 27617959, 2016). "In PBMCs of patients with acute coronary syndrome, in-vitro simvastatin 10 μM was able to increase the percentage of CD4 + CD25 + FoxP3+ regulatory T cells to total CD4+ cells." (PMID 26822994, 2016). "CD4+CD28− T cells detected in acute coronary syndrome patients express enhanced levels of OX40 and 4-1BB compared to their CD28+ counterparts." (PMID 25834833, 2015).
acute coronary syndrome (continued). "CD4+ CD28− T cells also called CD28 null cells have been reported as increased in the clinical setting of acute coronary syndrome." (PMID 25997053, 2015). "At the current state there are only data available regarding the role of hHSP-60 in activation of CD4+CD28− T cells in acute coronary syndrome patients." (PMID 25834833, 2015). "Previous studies have shown that naturally occurring CD4+CD25+ Tregs are down-regulated in patients with acute coronary syndrome (ACS)." (PMID 24558424, 2014). "Consistent with this purported function, it has been previously shown that acute coronary syndrome (ACS), a chronic inflammatory disease, is associated with a reduction in the number and function of circulating “classical” CD4+CD25+FOXP3+ Tregs." (PMID 24558424, 2014). "It is interesting in this context that KIR2DS4 molecule was expressed on remarkable proportion of CD4+CD28− T cell clones isolated from an acute coronary syndrome patient." (PMID 23028591, 2012). "Moreover, CD4+ T-cell subtypes are dysregulated and can serve as a prognosis biomarker in acute coronary syndrome (ACS) patients who have undergone percutaneous coronary intervention (PCI)." (PMID 41458980, 2025). "The present study aims to point out the implication of the immunological condition, assessed by the CD4+ nadir, on the outcome of HIV-infected patients with the associated acute coronary syndrome, expressed by the complexity and severity of the coronary lesions at angiography." (PMID 37627941, 2023). "Acute coronary syndrome with atypical presentation is common in PLWHs, although there are no available exact data on the prevalence of atypical angina in these patients, especially related to the CD4+ cell count." (PMID 37627941, 2023). "Besides, it was shown that more than 50% of cultured CD4+CD28− T cells from patients suffering from acute coronary syndrome recognize the 60 kD human heat-shock protein (hHSP-60), an ubiquitously expressed intracellular chaperone protein." (PMID 25834833, 2015). "The comparison with our study may not be relevant due to the fact that the mentioned study did not include HIV patients with the associated acute coronary syndrome, and the reference value for the nadir of CD4+ in this study was higher (350 cells/mm3)." (PMID 37627941, 2023). "In acute coronary syndrome, there is a systemic increase in CD4+ and CD8+ T lymphocytes, along with CD4+ Th1, Th2, Th17, and Treg subsets in cardiac, circulatory, and lymphoid tissues." (PMID 38921319, 2024). "The functional role and mechanism of KIRs are still elusive but a subtype of this family, KIR2DS2, was detected on the surface of CD4+CD28− T cells from RA and acute coronary syndrome patients." (PMID 25834833, 2015). "About 50% of the CD4+CD28null, T-cell clones derived from patients with acute coronary syndrome recognize HSP60, and when stimulated with autologous HSP60, CD4+CD28null T-cell clones produce IFN-γ and perforin." (PMID 24347824, 2013). "CD4+ T cell-mediated immune responses are involved in the development of CAD and affect the stability of atherosclerotic plaques through the secretion of interferon (INF-γ) in Th1 cells, leading to acute coronary syndrome (ACS)." (PMID 36970364, 2023). "We recently uncovered that the percentage of naturally occurring CD4+CD25+Tregs and CD4+LAP+Tregs are reduced in patients with acute coronary syndrome (ACS) and that the number and function of CD4+LAP+Tregs are decreased in patients with dilated cardiomyopathy." (PMID 36405994, 2022). "Furthermore, it has been reported in patients with rheumatoid vasculitis and in patients with an acute coronary syndrome that CD4+CD28null T cells expressed KIR2DS2 in the absence of opposing inhibitory receptors of the same specificity." (PMID 30995924, 2019).
acute coronary syndrome (continued). "CD4+ latency-associated peptide (LAP)+ regulatory T cells (Tregs) are a newly discovered T cell subset in humans and the role of these cells in patients with acute coronary syndrome (ACS) has not been explored." (PMID 24558424, 2014). "For example, CD8+ large granular lymphocytes as well as CD4+,CD28null T cells are more common in RA patients, particularly those with extraarticular disease, and the latter T cells are also found in patients without RA who have acute coronary syndromes." (PMID 18240242, 2008). "Indeed, CD4+CD28null T cells were significantly higher in patients with CAD and co-existent RA than in controls with stable angina (P = 0.001) and reached levels found in patients with acute coronary syndromes." (PMID 16207339, 2005). "Indeed, T cells in patients with acute coronary syndromes (ACS) are skewed toward the production of interferon (IFN)-γ, a potent monocyte activator largely derived from a distinct subset of CD4+ T cells that, in contrast to classic CD4+ helper T cells, lacks the costimulatory molecule CD28." (PMID 16207339, 2005). "A subset of CD4+ T-cell lacking CD28 expression (representing 5–23% of all CD4+ T-cells) and producing high levels of IFNγ and tumor necrosis factor (TNF)α have been found in the plaques from patients with acute coronary syndrome (ACS)." (PMID 33297441, 2020). "Additionally, detailed analysis of CD4+ T-cells in acute coronary syndromes (ACS) revealed the expansion in peripheral blood of an unusual subset, that does not express the co-estimulatory receptor CD28 (CD4+CD28null)." (PMID 26693103, 2015).
dry eye (39 papers, 2011 to 2025). "In animal models, excessive transfer of CD4 + T cells in dry eye mice exacerbates symptoms in Treg-deficient mice, confirming the suppressive role of Treg cells in dry eye conditions." (PMID 38898418, 2024). "In another report, the adoptive transfer of CD4+ T cells from wild-type C57BL/6 mice with dry eye (enriched in Th1 cells) into RAG1-deficient mice induced corneal epithelial apoptosis by a mechanism that involves IFN-γ secretion at the ocular surface." (PMID 37217914, 2023). "Nevertheless, a mouse model of AIRE gene deficiency showed that deficient mice experienced loss of nerve innervation in the cornea and the lacrimal gland, which was associated with spontaneous, CD4+ T-cell mediated exocrinopathy and aqueous-deficient dry eye." (PMID 33413189, 2021). "Mice deficient in the autoimmune regulator (Aire) gene developed spontaneous, CD4+ T cell-mediated exocrinopathy and aqueous-deficient dry eye that were associated with loss of nerves innervating the cornea and lacrimal gland." (PMID 28926640, 2017). "Such autoreactive CD4+ cells are sufficient to induce dry-eye phenotype once adoptively transferred in T-cell-deficient but otherwise healthy nude mice." (PMID 28091781, 2017). "We have previously reported that our experimental dry eye model causes an influx of pathogenic CD4+T cells, and a significant decrease in CD8α cells in the conjunctival epithelium when these cells are counted infiltrating the goblet cell rich area." (PMID 22590618, 2012). "We used the CD4-DNTGFβRII strain as a model to study T cell unresponsiveness to TGF-β by creating an experimental dry eye where CD4+T cells have been shown to have a pathogenic role." (PMID 22194977, 2011). "We have developed and characterized this environmental stress model of dry eye that induces infiltration of the conjunctiva with a mix of Th-17 and Th-1 pathogenic CD4+ T cells." (PMID 22194977, 2011). "Likewise, CD25-deficient mice with Sjögren-like keratoconjunctivitis sicca displayed increased CD4+ and CD8+ T cells in conjunctiva, along with elevated IL-17A and CCL20 mRNA expression in corneal and conjunctival tissues compared with wild-type mice." (PMID 41300932, 2025). "Secondly, when the chemokine receptor CXCR3 (along with CCR5) expressed by Th1 cells binds to their specific ligands, such as INF-γ, they act as a central mediator to coordinate the localization of CD4+ T cells to the ocular surface to perform an immune response, causing dry eye occurrence." (PMID 36522768, 2022). "We hypothesized that the initiation of the immune response that generates pathogenic CD4+T cells and contributes to the dry eye phenotype is dependent on desiccating-stress induced TGF-β1 production and not on constitutive levels of TGF-β1." (PMID 22194977, 2011). "Two subsets of CD4(+) T cells, Th1 and Th17, have been identified as primary drivers for desiccative stress-induced dry eye." (PMID 40255803, 2025). "A role for CD4 + T cells in dry eyes has been demonstrated, with clinical and animal models showing increased Th1 and Th17 cells and decreased Treg cells in T cell subsets." (PMID 38898418, 2024). "In ocular allergy, Th2 cell-derived cytokines increase corneal epithelial permeability, whereas Th17 CD4+ T cells disrupt the corneal epithelial barrier in dry eye." (PMID 37217914, 2023). "The infiltrate contains CD4+ Th cells, B cells, and plasma cells leading to glandular dysfunction that manifests as dry eyes and dry mouth." (PMID 35511824, 2022). "Abatacept, a CTLA4-Iginitially developed as a competitive inhibitor of CD28/B7 pathway that acts against CD4 + T-cells, better impacts dry eyes and mouth." (PMID 33917955, 2021). "The main proliferating subset of dry eye T cell effectors in the presence of T regulatory cells is IL-17-secreting CD4+ T cells." (PMID 34578864, 2021).
dry eye (continued). "Fecal microbiota transplant from conventional mice reverted dry eye phenotype in germ-free mice and decreased CD4+IFN-γ+ cells to levels similar to conventional C57BL/6J mice." (PMID 29438346, 2018). "In the present, we investigated the expression of CD4 + T-cells in lacrimal gland in an experimental dry eye mouse model." (PMID 28785037, 2017). "Previous studies further demonstrated that the numbers of CD4+CD25+FoxP3+Tregs play a crucial role in the pathology of dry eye." (PMID 28091781, 2017). "The degree of CD4+ T cell infiltration was inversely correlated with the conjunctival goblet cell density in desiccating stress-induced dry eye." (PMID 27313829, 2016). "In order to investigate the role of chemokine receptors in the migration of CD4+ T cells from the regional lymph nodes to the OS, we examined the phenotype of disease in chemokine receptor knock out (KO) mice in our dry eye animal model." (PMID 24223818, 2013). "Keratoconjunctivitis sicca was seen commonly in patients with a CD4+ T cell count of 200–499 cells/μl (42.6%)." (PMID 23710936, 2013). "Two subtypes of CD4+ T cells, Th1 and Th17 cells, function concurrently in dry eye to mediate disease." (PMID 24223818, 2013). "RAG1KO recipients of adoptively transferred CD4+T cells isolated from DS5 CD4-DNTGFβRII showed milder dry eye phenotype and less conjunctival inflammation than recipients of WT control." (PMID 22194977, 2011). "To evaluate the contribution of TGF-β1 to the ocular surface immunopathology in dry eye, we challenged CD4-DNTGFβRII mice with a desiccating environment." (PMID 22194977, 2011). "We observed development of a spontaneous dry eye phenotype in the CD4-DNTGFβRII mice with aging from 8–14 weeks, with increased corneal surface irregularity, T cell infiltration in the cornea and conjunctiva and corneal barrier disruption." (PMID 22194977, 2011). "CD4+ cells were evident in the limbus (a vascularized structure surrounding the cornea), and their numbers were significantly increased after induction of dry eye in accord with the inflammatory nature of the disease." (PMID 37130912, 2023). "Furthermore, in vivo neutralization of IL-17A ameliorates dry eye and adaptive transfer of CD4+ IL-17A producing cells induces the disease in naïve mice in several models." (PMID 37130912, 2023). "By contrast, the same event or the corresponding activation of Th17 CD4+ in dry eye or Th2+ CD4+ T cells in the setting of ocular allergy promote corneal epitheliopathy in combination with other pathogenic factors (desiccation or allergen-specific effects, respectively)." (PMID 37217914, 2023). "In line with this, we observed fewer activated macrophages (professional antigen-presenting cells), fewer proinflammatory Th1 CD4+ T cells, and more regulatory CD4+ T cells, in agreement with our previous publications that these cells are important players in age-related dry eye." (PMID 37540176, 2023). "Importantly, the main proliferating subset of dry eye-T cell effectors in the presence of T regulatory cells is IL-17 secreting CD4+ T cells." (PMID 34575516, 2021). "CD4+ T cells are essential to pathogenesis of ocular surface disease in dry eye." (PMID 24223818, 2013). "Concerning the ocular microbiota, studies performed in animals have shown that two types of CD4+T lymphocytes with opposing immunological roles, T helper cells type 17 (Th17) and regulatory T cells (Treg), interact with the resident microbiota of the eye and have been related to dry eye syndrome." (PMID 37686143, 2023). "Infiltration of CD4+ T cells at the limbus and the levels of inflammatory cytokines in tears may play an important role in inhibiting corneoscleral stem cell metabolism in dry eye patients." (PMID 26925258, 2016). "Of note, FMT from wild-type C57BL/6J mice was sufficient to reduce the CD4+ IFN-γ+ T cell infiltration and to recover the dry eye phenotype, suggesting the feasibility of this approach in the context of eye-related diseases." (PMID 37686143, 2023).